CD4 (CD4 molecule)
Diseases named in the same sentence as CD4 in open-access papers (continued):
Sharing a sentence is not in itself a finding about the gene and the disease.
tumor (continued). "Later, the IL-2-depleted microenvironment induces the differentiation of some activated CD4+ T cells into CXCL13-producing Tfh, capable of sustaining TLS formation and tumor-infiltrating B cell recruitment." (PMID 35874810, 2022). "Repetitive tumor challenge with Raji cells induced profound CAR T degranulation, as demonstrated by increased levels of CD107 expression in both CD4+ and CD8+ cells." (PMID 35406703, 2022). "We investigated the infiltration of tumor tissue by host T cells and microglia/macrophages using the well-established markers CD3, CD4, CD8 (column 3–5), CD11b, CD204, and CD163 (column 6–8)." (PMID 36358353, 2022). "More importantly, both CD8+ and CD4+ T cells recognized physiologic levels of antigen presented by tumor cells meaning patients were treated with functional CD8+ and CD4+ T cells." (PMID 35335089, 2022). "The general multiplexing TILs immunofluorescence staining protocol was used to simultaneously detect cytokeratin positive tumor cells and major TIL subtypes, namely CD4+ T, CD8+ T, and CD20+ B cells." (PMID 35661148, 2022). "Consistent with the results of immune infiltration analyses, responders (CBP_low) had a higher rate of anti-tumor immune subsets, such as elevated M1/M2 macrophage ratio, increased CD8+ T cells and CD4+ T cells." (PMID 36291668, 2022). "The APC induces numerous systemically available molecules (cytokines, chemokines), as well as NK, CD4+ and CD8+ cells and γδT-cells to form a complete tumor-specific immune arsenal which can be used against the malignant cells." (PMID 35681533, 2022). "The cancer neoantigen vaccine can induce specific CD4+ and CD8+ T cells to target specific patient tumours, and in further clinical trials, it is expected that the effect of the vaccine will be satisfactory." (PMID 35592424, 2022). "TCOF1 was correlated with tumor purity, CD8+ T cells, CD4+ T cells, B cells, neutrophils, macrophages, and dendritic cells (DCs) in 6, 14, 16, 12, 20, 13, and 17 cancer types, respectively." (PMID 35093935, 2022). "It is possible to reverse the exhausted phenotype of CD4+ T and CD8+ T cells after inhibiting its expression using anti-CD73 monoclonal antibody, which also blunted the tumor growth." (PMID 36466881, 2022). "In parallel, we used multispectral immunofluorescence to confirm the localization of the CD8+, CD4+, FOXP3+, CD31+, and F4/80+ populations within the tumor 15 days after Delta-24-ACT treatment." (PMID 35393952, 2022). "Virotherapy has the potential to significantly boost the infiltration of CD4+ and CD8+ T lymphocytes as well as the release of IFN-γ and TNF-α in tumor tissues." (PMID 36703982, 2022). "Our results revealed that the infiltration of 28 subtypes of immune cells, except for effector memory CD4+ T cell and eosinophil, were significantly higher in PCP tumor tissues than in normal brain tissues." (PMID 36389809, 2022). "We found that the interaction of effector CD4 T cells with TAM, a cell type previously extensively studied because of its role in promoting angiogenesis, metastasis, and tumor stem cell survival, can result on tumor rejection." (PMID 35903540, 2022). "Antigenic vaccines are designed to activate the immune response by increasing antigen-specific CD4+ and CD8+ T cells after vaccination, ultimately mediating the regression of tumor cells." (PMID 36092724, 2022). "In contrast, in CHSY3 expressing “+”, tumour peripheral CD3+ T cells, CD4+ T cells and CD8+ T cells clustered less and more immune cells penetrated the stroma into the tumour parenchyma." (PMID 35571047, 2022). "Multiple in vitro studies show that the presence of CAFs significantly reduces the proliferation of both CD4+ and CD8+ T cells in a contact-independent manner, suggesting this as a possible explanation for reduced TIL frequencies in CAF high tumours." (PMID 35479076, 2022).
tumor (continued). "Although NK cells lack a direct ability to curb the growth of metastatic foci in the lungs, they regulate CD4+ and CD8+ T cell recruitment to the lungs, which infiltrate and control the in situ metastatic tumor growth in the lungs." (PMID 36733396, 2022). "Hemoglobin, serum albumin and creatinine, the CD4+/CD8+ ratio, and tumor size were entered into Cox regression analyses." (PMID 35804319, 2022). "The proportion of tumor-infiltrating lymphocytes (TILs; CD45+CD3+ cells), CD3+/CD8+ ratio, and CD3+/CD4+ ratio were also similar." (PMID 36246841, 2022). "Flow cytometry of single cell tumor suspensions to evaluate for TIL revealed a trend towards greater infiltration of CD45+, CD45+ CD3+ and CD4+ cells with BATs compared to all other treatment groups that neared significance (p = 0.057)." (PMID 35177811, 2022). "In conclusion, our immunohistochemistry results showed that CD4+ T cells were equally distributed throughout the stroma, whereas CD8+ T cells were localized more distantly from the tumor nests." (PMID 35954489, 2022). "As a proportion of all CD45+ immune cells in the brain, significant increases in cDCs, CD4+ T cells, CD8+ T cells, and activated microglia were observed in tumor-bearing brains compared to healthy brains." (PMID 35309309, 2022). "mIHC with CD3, CD4 and CD8 T-cell markers revealed distinct patterns of T-cell infiltration in the different tumor subtypes." (PMID 36185254, 2022). "To delineate the amounts of T cells of normal and tumor tissue in PTC-W and PTC-WO, we evaluated immunohistochemical staining of CD3, CD4 and CD8 on all 80 tumor samples and 40 normal samples from 40 patients in immunohistochemistry analysis." (PMID 35720279, 2022). "Numerous antigens, including self-antigens, are expressed by tumors, but infiltrating (CD4 + CD25 + Foxp3 +) Treg cells dampen the immune response, stopping it from attacking tumor cells." (PMID 34275008, 2022). "The present work demonstrated that the single administration of DCs transduced for the production of IL-12 and/or IL-18 increases the influx and activity of CD4+ and CD8+ T lymphocytes and decreases CD11b cells into the tumor microenvironment." (PMID 35372586, 2022). "To explore the differences of anti‐tumor immunity, we performed CD45, CD4, and CD8 staining in mouse tumor tissues." (PMID 35762456, 2022). "Tumor-infiltrating lymphocytes include B cells (CD20+), helper T cells (CD4+), cytotoxic T cells (CD8+), and regulatory T cells (Tregs, FOXP3+)." (PMID 35433771, 2022). "By contrast, HPV infection downregulates CXCL14, leading to a possible suppression of the chemotaxis of NK, CD4+ T, and CD8+ T cells, which in turn suppresses the anti-tumor immune response in the TME." (PMID 35740551, 2022). "It is important to note that many CD4+, CD8+, and CD68+ cells were infiltrated into tumor tissues from humanized NDG mice." (PMID 35229723, 2022). "In peripheral blood, spleen and tumor tissues of the CT26 + Me49 group, as compared with the control group, the mean frequency of CD4+ T cells was significantly reduced (p < 0.0001)." (PMID 35600363, 2022). "CD4+ T cells can enhance the function of tumor specific CD8+ T cells by secreting interleukin-2, which can effectively promote tumor regression." (PMID 35577774, 2022). "Interferon gamma (IFN-γ) is a cytokine secreted by CD4+ T cells, CD8+ T cells and NK cells that plays a major role in tumor cell recognition and destruction through different pathways." (PMID 35625811, 2022). "We have also demonstrated that the prevalence of CD3−/CD94+ NK cells and CD8+ cytotoxic T cells were greater in advanced tumor stages III and IV, whereas that of CD4+ T helper cells was decreased." (PMID 36428793, 2022). "The immune status pre-treatment was evaluated by CD4+ and CD8+ T cell tumor infiltration and expression of MHC-1 and PD-L1." (PMID 35740542, 2022).
tumor (continued). "BTLA expression on CD4+ T cells and CD8+ T cells in the tumor microenvironment of EOC was also studied, which was 37.6% and 15.7%, respectively." (PMID 35204342, 2022). "Corresponding to these results, enhanced memory CD4+ and CD8+ T cells in tumor infiltrating lymphocytes (TILs), peripheral blood and spleen were observed in the tumor-bearing mice receiving high-dose and low-frequency αPD-L1 treatment." (PMID 36220994, 2022). "TAMs can secrete cytokines and chemokines such as C-C chemokine ligand (CCL) 3, CCL4, TGFβ, and IL10, which recruit regulatory T cells (Tregs) to the TME and suppress the function of CD4+ and CD8+ T cells, thereby promoting tumour progression." (PMID 36497148, 2022). "CD4+ helper T cells and cytotoxic CD8+ T cells play an important role in tumor prevention by targeting antigenic tumor cells, and CD8+ T cells are associated with better clinical outcomes and response to immunotherapy in many cancers." (PMID 36052245, 2022). "T cell responses were analyzed through immunohistochemistry (IHC) staining for CD3, CD4, CD7, CD8, CD25, TIA‐1, HLA‐DR, and Ki67 (proliferative marker) on tumor biopsy samples." (PMID 35790025, 2022). "The ratio of effector CD8+ T/Tregs cells and cytokine-producing IL-2+CD4+ and IFN-γ+CD8+ tumor-infiltrating T cells increased in the spleen and TME after treatment of specific B. bifidum strains with PD-1 treatment." (PMID 35355998, 2022). "The CD4+Th1/CD4+Th2 balance plays an important role in the tumor microenvironment, and our results showed that high expression of RIOK2 was negatively correlated with CD4+Th1/CD4+Th2 cells, indicating that RIOK2 is involved in Th1/Th2 regulation." (PMID 36518977, 2022). "The CD4 and CD8 regulatory T lymphocytes are immune cells with negative regulating role in anti-tumor immunity through participating in tumor cell escape, immune surveillance and defense." (PMID 35986302, 2022). "Particularly, tumor-infiltrating lymphocytes (TILs) are detected in 75% of OS with a peak around 86% in metastases, they include CD8+ T lymphocytes, CD4+ T lymphocytes, CD20+ B lymphocytes, and CD117+ mast cells." (PMID 35433427, 2022). "It has been established that the presence of immune suppressing cells, such as CD4 + FoxP3 + T regulatory cells (Tregs), in the TME can impede T cell immunity and contribute to tumor progression." (PMID 35962391, 2022). "CD4+ Tregs have a role in cancer progression by suppressing both CD4+ and CD8+ effector responses and exerting various other immunosuppressive effects on the tumor microenvironment (TME)." (PMID 36159781, 2022). "In F4/80lowLy6Clow macrophage co-injected tumor, the F4/80lowLy6Clow macrophage proportion was higher and the proportions of tumor-infiltrating CD3+ and CD4+ T cells were lower, compared to those in F4/80highLy6Clow macrophage co-injected tumor." (PMID 36470862, 2022). "To identify cells producing CXCL13 involved in TLS formation, we performed RNA ISH double staining (CXCL13 and CD4+ T cells, CXCL13 and CD8+ T cells) using HGSC tumor specimens." (PMID 35552285, 2022). "Dendritic cells (DCs) are professional antigen-presenting cells with the distinctive property of inducing the priming and differentiation of naïve CD4+ and CD8+ T cells into helper and cytotoxic effector T cells to develop efficient tumor-immune responses." (PMID 35267487, 2022). "Considering immune infiltration, tumour areas with a higher FDG uptake had higher levels of T-lymphocytes (CD3+ and CD4+/CD8+) and macrophages (CD68+/CD163+) compared to areas with a lower uptake." (PMID 36143097, 2022). "Quantitative analysis revealed that chemohormonal therapy significantly increases the intratumoral infiltration of CD3+CD4+ T cells, CD3+CD8+ T cells, and CD103+CD8+ tumor-resident T cells." (PMID 35836810, 2022). "CCR8 expression level in Tregs was highest in tumor tissues and higher than in FOXP3− conventional CD4 T cells (conv CD4 T cells)." (PMID 35354899, 2022).
tumor (continued). "For example, miR-214 secreted by tumors can facilitate CD4+ CD25highFoxp3+ Tregs expansion by targeting PTEN and inducing IL-10 secretion, leading to host immune suppression and rapid tumor growth." (PMID 34968167, 2022). "Tumor infiltrating CD8+ T cells and CD4+ T cells in MC38 tumors from B-hTNFR2 mice were detected with by immunohistochemistry (IHC)." (PMID 35251028, 2022). "In order to trigger an effective antitumor response, tumor antigens must be taken up by DCs and presented through MHC-II and/or MHC-I to activate CD4+ T cells and CD8+ T cells, respectively." (PMID 35355998, 2022). "This normalization is caused by a VEGF pathway inhibitor, resulting in increased tumor infiltration lymphocytes, such as CD4+ and CD8+ T cells, into the tumor parenchyma." (PMID 36430176, 2022). "As another example, an “immune inflamed” phenotype is characterized by infiltration of CD4+ and CD8+ T cells in the tumor parenchyma and has been correlated with increased OS across tumor types." (PMID 35585623, 2022). "These activated CCR6+ILC3s can secrete CXCL10 that promotes CD4+ and CD8+ T cells migration to the tumor, enhancing anti-tumor immunity and response to immune checkpoint blockade." (PMID 36341381, 2022). "Contrastingly, different from CD4 + CAR-T cells, the conventional CD8 + CAR-T cells slightly increased the expression of CD98 and GOT2 after tumor challenge." (PMID 35869100, 2022). "The effector memory of CD4+ T cells and the amount and CD80 expression of macrophages were enhanced in both the TC1 and C3PQ tumor models." (PMID 35356198, 2022). "More importantly, the CD4+ and CD8+ T cell immunity were also amplified to result in sufficient inhibition of 4T1 tumor progression." (PMID 37323705, 2022). "In our work, the subpopulation composition of tumor-infiltrating T-lymphocytes (CD4+, CD8+, CD45RO+) for eight tumor tissue samples was characterized by immunohistochemistry." (PMID 36358722, 2022). "T cells or NK cells in the peripheral blood showed a pattern similar to that of tumor samples, indicating that Q702 treatment increased the proportion of IFN-γ-producing CD4 T and NK cells and granzyme B+ CD8 T cells." (PMID 36230744, 2022). "Five of eight CAIX+ tumors had increased CD4+ and CD8+ T-cell infiltration into the CAIX+ areas, whereas in three tumors, the opposite pattern was observed, with CD4+ and CD8+ T cells being mostly excluded from the CAIX+ tumor regions." (PMID 36185254, 2022). "A marked reduction in the percentage of CD8+ T lymphocytes and a significant increase in the frequencies of CD4+ T lymphocytes and CD4+ and CD8+ T lymphocytes expressing PD1 and CD39 were evident in tumor tissue in comparison with the normal breast tissue." (PMID 35051220, 2022). "Cytotoxic immune cells in BC, namely CD4+ T and CD8+ T cells, killed tumour cells by recognising MHCII and MHCI, respectively." (PMID 36159866, 2022). "Further results showed that the number of regulatory T cells (Treg) (CD4+CD3+Foxp3+) decreased, the immunosuppressive tumor microenvironment was relieved, and immune T cells induced antitumor immunity was activated." (PMID 35651605, 2022). "The DP CD4+ Th cells were primarily found in the TME, had an activated phenotype, and were proliferating in the tumor." (PMID 35439168, 2022). "Immunohistochemical staining of the tumor tissue of one 64-year-old female LUAD patient showed some degree of protein expression of both CCL17 and CD4 (CD4+ T cell marker molecule)." (PMID 35321241, 2022). "Severe necrosis and infiltration of NK cells, as well as CD4+ and CD8+ T cells, were observed in RdB/IL-12/IL-18-treated tumour tissues." (PMID 36140243, 2022). "We then assessed the tumor-infiltrating T cell population by double staining tumor tissue with CD3 and CD4 (to detect CD4+ T cells) or CD3 and CD8 (to detect CD8+ T cells)." (PMID 36246355, 2022).
tumor (continued). "Upon histopathological analysis, along with histopathological classification and staging, the degree of CD4, CD8, and CD163 cell infiltrations and expressions of interleukin-6 and matrix-metalloproteinase-11 (MMP-11) in the primary tumor were assessed." (PMID 36010928, 2022). "The primary function of infiltrating B cells in anti-tumor immunity is their capacity to deliver antigens to CD4+ and CD8+ T cells, thus forming an antigen-specific immune response in the tumor micro-environment." (PMID 36230580, 2022). "The final effector mechanism leading to tumor elimination is produced by the cytotoxic CD8+ T cell population, which is supported by CD4+ T helper (Th1) cells through the production of IL2 and IFN and is associated with a positive prognosis." (PMID 35328602, 2022). "The immune-inflamed phenotype was characterized by enrichment of various immune cells like CD4+ T cells, CD8+ T cells, and monocytic cells in the tumor parenchyma, as well as many proinflammatory and effector cytokines." (PMID 35418978, 2022). "The larger populations of CD4+ cells and CD8+ cells and increased serum levels of sPD-L1 in patients’ peripheral blood with GHPA suggest that the tumor not only affects the TIME but also profoundly exerts systemic effects involving immunity." (PMID 34647152, 2022). "Tregs are a specialized subset of CD4 T cells, which are identified by the expression of the FOXP3 gene, and are responsible for immune suppression and tumor tolerance by the production of TGF-β and suppression of effector T cells." (PMID 33422072, 2021). "At last, we evaluated the degree of infiltration of different immune populations (CD8+ T cells, CD4+ T cells, B cells and macrophages) with respect to the TMB of each tumor." (PMID 33963008, 2021). "T cells play a crucial role in immunosurveillance; CD8+ T cells can directly eliminate neoplastic cells, and CD4+ T cells collaborate with macrophages, NK cells and CD8+ T cells to mount anti-tumor immune responses." (PMID 34884543, 2021). "We observed a significant decreased in the percentages of CD4+ and CD8+ T cells in the lungs and peripheral blood of Fstl1+/- tumor free mice." (PMID 33639614, 2021). "The TCR.strong metric has been predicted using a CD4+ T cell system and then applied at the bulk tumor level, therefore the extent to which this metric is modified in CD8+ versus CD4+ T cells (or potentially other cells) remains to be determined." (PMID 34534438, 2021). "Immunohistochemistry staining of CD4, CD8, F4/80and Ly6G on DEN + CCl4 tumors further confirmed the reshaping of the tumor microenvironment." (PMID 34593796, 2021). "The co-delivery had a range of effects including increased tumor infilitrating lymphocytes and altering CD8+/CD4+ T cell ratios and CD8+/Treg ratios." (PMID 34688033, 2021). "The well-characterized anti-tumor role of CD8+ T cells has long been prioritized for immunotherapy; however, the advantages of transferred cytolytic CD4+ T cells to immune activation are receiving more attention." (PMID 34795224, 2021). "Tumor IMmune Estimation Resource results noted that GNPNAT1 expression was negatively correlated with B cells (R = −0.304, P = 8.04e-12), CD4+ T cells (R = −0.218, P = 1.24e-06), and dendritic cells (R = −0.137, P = 0.002)." (PMID 33842535, 2021). "Contralateral tumor harvested at 7 days showed significant increase in CD3+CD8+IFNγ+ and CD3+CD4+IFNγ+ T cells over ablation alone and untreated control, while T-regulatory cell population decreased in frequency." (PMID 33668932, 2021). "Priming of tumor-specific CD8+ T cells and CD4+ T helper (Th) 1 cells is key to mounting an effective immune response." (PMID 34203869, 2021). "In the tumor context, MHC class II molecules can present antigenic peptides recognized by CD4+T cells." (PMID 35003090, 2021).